TNC (tenascin C)
Diseases named in the same sentence as TNC in open-access papers (continued):
Sharing a sentence is not in itself a finding about the gene and the disease.
lung fibrosis (22 papers, 2011 to 2025). "It is a well-known profibrotic molecule with genetic deletion of TNC being associated with reduced lung fibrosis and reduced pressure-overload-induced cardiac fibrosis and myocyte hypertrophy." (PMID 35406763, 2022). "Not only do tenascin-C-deficient mice have an attenuated response to bleomycin-induced lung fibrosis, but this process has also been shown to be TLR4 dependent." (PMID 34258628, 2021). "Tenascin-C was higher in scleroderma patients compared to healthy controls Patients with pulmonary fibrosis involvement had the highest levels." (PMID 38077374, 2023). "The role of TNC in promoting pulmonary fibrosis is also supported by attenuation of bleomycin-induced fibrosis in Tnc-deficient mice." (PMID 32332792, 2020). "α-SMA, a marker of epithelial to mesenchymal transition, and Tenascin-C (TN-C), both of which are indicators of pulmonary fibrosis, are highly expressed in the adult lung parenchyma after ALI." (PMID 32596244, 2020). "Bleomycin-induced lung injury appeared to engender a stronger fibrotic response in Spic−/− mice than in WT mice based on the expression of collagen 1a1 and Tenascin C, two markers of lung fibrosis." (PMID 32610126, 2020). "Extracellular matrix protein and gene expression of markers involved in lung fibrosis (tenascin-c, fibronectin, collagen I [COL1A1], collagen III [COL3A1] and α-smooth muscle actin [α-SMA]) were analyzed." (PMID 29703175, 2018). "Together, results from these morphological, biochemical and functional assays demonstrate, for the first time, that TNC−/− mice are largely protected from skin and lung fibrosis." (PMID 27256716, 2016). "Immunohistochemistry demonstrated that enhanced LOX expression in bleomycin-induced lung fibrosis was significantly attenuated in TNC−/− mice." (PMID 27256716, 2016). "The present results indicate that persistent tenascin-C deposition contributes to the pathological persistence of skin and lung fibrosis, and is along with TGF-β, CCN2 and others, a major factor in the process." (PMID 27256716, 2016). "Tenascin-C, an extracellular matrix glycoprotein expressed during wound healing, is a marker of both pulmonary fibrosis and hepatitis." (PMID 27590145, 2016). "While Fn-EDA and tenascin-C are extracellular DAMPs contributing to ECM stiffness implicated in pulmonary fibrosis, we know of no study that investigated the relationship between ECM stiffness and induction of profibrotic DAMPs at the cellular level in macrophages or fibroblasts." (PMID 34258628, 2021). "Specifically distinguishing was the behaviour of TNC, a protein that is known to be upregulated in response to inflammation and tissue remodelling, particularly also in the BLM lung fibrosis model." (PMID 24260575, 2013). "While our in vitro findings in adult Human lung fibroblasts showed that PRRX1 inhibition mainly impacted ACTA2 expression levels, Prrx1 ASO treatment in the bleomycin mouse model of lung fibrosis also inhibited the deposition of ECM proteins such as Collagen 1, Fibronectin, Tenascin C, and Elastin." (PMID 37261432, 2023). "COMP, a non-collagen ECM protein, and TNC are both upregulated in the context of pulmonary fibrosis, which JUN signaling also mediates." (PMID 32792541, 2020). "Mice lacking tenascin-C show attenuation of skin and lung fibrosis, and accelerated fibrosis resolution." (PMID 27256716, 2016). "The present studies showed that bleomycin-induced skin and lung fibrosis, and spontaneous hypodermal fibrosis in the Tsk/+ mouse, were ameliorated in the absence of tenascin-C, and TNC−/− mice showed accelerated fibrosis resolution." (PMID 27256716, 2016). "Additionally, studies demonstrated that the weakening of skin and lung fibrosis occurred, and the resolution of fibrosis was accelerated in mice lacking tenascin-C." (PMID 39114190, 2024).
lung fibrosis (continued). "Furthermore, we also found that LPS‐induced expressions of extracellular matrix genes such as TNC and HYAL1, as well as a vasopressor gene, EDN1, all of which are involved in the process of lung fibrosis, were also dose dependently downregulated by antofine treatment." (PMID 28805975, 2017). "Lung fibrosis was accompanied by substantial collagen accumulation, and tenascin-C deposition within the interstitial matrix of thickened alveolar septae, whereas no tenascin-C was detectable in the lungs from TNC−/− mice." (PMID 27256716, 2016).
rheumatoid arthritis (22 papers, 2009 to 2025). A chronic, systemic autoimmune disorder characterized by inflammation in the synovial membranes and articular surfaces. "However, persistent expression of tenascin-C is linked to various pathological conditions, including rheumatoid arthritis (RA), scleroderma, and some fibrotic diseases." (PMID 39114190, 2024). "They reported a median serum tenascin C level of 118.2 ng/mL in rheumatoid arthritis and 53.8 ng/mL in AS." (PMID 40564778, 2025). "It has been determined that tenascin-C level is increased in rheumatic inflammatory diseases such as rheumatoid arthritis (RA), systemic lupus erythematosus, and systemic sclerosis." (PMID 39114190, 2024). "Neither total nor splice-specific tenascin-C levels correlated with the presence of autoantibodies to citrullinated tenascin-C in rheumatoid arthritis (RA) patients." (PMID 38077374, 2023). "Cathepsin B overexpression results in the onset of osteoporosis, rheumatoid arthritis, and certain forms of cancers due to the excessive degradation of the proteins aggrecan, tenascin C, fibronectin, and collagen type 1." (PMID 34827106, 2021). "Increased TNC expression was also found in lungs with progressive idiopathic pulmonary fibrosis, and in synovium with arthritis such as rheumatoid arthritis." (PMID 34901073, 2021). "High serum levels of tenascin-C are found in many inflammatory diseases such as rheumatoid arthritis, collagen disease, rheumatoid myocarditis and systemic lupus erythematosus." (PMID 30442110, 2018). "We investigated whether citrullinated tenascin-C (cTNC), an extracellular matrix protein expressed at high levels in the joints of patients with rheumatoid arthritis (RA), is a target for the autoantibodies in RA." (PMID 26659718, 2016). "A third class of endogenous activator is the large extracellular matrix protein tenascin C. Tenascin C is induced by tissue damage and the C-terminal fibrinogen globe (FBG) module causes activation of TLR4 in chronic inflammatory disease such as rheumatoid arthritis." (PMID 25339952, 2014). "In this article, we present a comparative immunohistochemical evaluation of four clinical-stage antibodies (L19, F16, G11 and F8) directed against splice isoforms of fibronectin and of tenascin-C for their ability to stain synovial tissue alterations in rheumatoid arthritis patients." (PMID 19781067, 2009). "For instance, the autocrine and paracrine interactions between α9β1 integrin and tenascin-C within the joint tissue microenvironment are pivotal in the pathogenesis of rheumatoid arthritis (RA)." (PMID 40153583, 2025). "We aimed to search for common features in the autoreactive T cell receptor (TCR) repertoire in patients with rheumatoid arthritis (RA), focusing on the newly identified candidate antigen citrullinated Tenascin C (cit-TNC)." (PMID 34972837, 2021). "Tenascin-C (TNC), an extracellular matrix protein that has proinflammatory properties, is a recently described antibody target in rheumatoid arthritis (RA)." (PMID 33507879, 2021). "Among them, tenascin C (TNC) might be related to chronic inflammatory processes, and certain evidence has been published in animal models as well as in patients with autoimmune diseases such as multiple sclerosis and rheumatoid arthritis." (PMID 40564778, 2025).
myocardial infarction (21 papers, 2012 to 2025). Gross necrosis of the myocardium, as a result of interruption of the blood supply to the area, as in coronary thrombosis. "Dysregulated expression of TNC has been associated with various cardiac pathologies, including hypertension, atherosclerosis, myocardial infarction, and heart failure." (PMID 37893006, 2023). "Animal studies have shown a link between TnC and many heart diseases, such as myocardial infarction, hypertensive fibrosis, myocarditis and cardiomyopathy." (PMID 41010873, 2025). "Anti-tenascin-C antibodies conjugated to iron oxide nanoparticles have been used as magnetic resonance imaging probes to detect myocardial infarction and atherosclerosis in mice." (PMID 34564696, 2021). "An 111In-labelled anti-tenascin-C antibody has been used to detect myocardial infarction in cynomolgus monkey hearts." (PMID 34564696, 2021). "In a myocardial infarction (MI) model of heart failure, expression of TnC L48Q before the MI preserves cardiac function and performance." (PMID 26908229, 2016). "In the mice model of permanent ligation of the coronary artery, ventricular remodeling in the TNC knockout mouse was significantly reduced and cardiac function was improved compared with the wild type at day 28 after myocardial infarction." (PMID 25883880, 2015). "Tenascin-C is an established early marker of remodeling and is also strongly involved during embryonic development or scar formation after myocardial infarction." (PMID 24971311, 2014). "Some members of the matricellular protein family (like tenascin-C, osteopontin, CCN1 and the galectins) have been implicated in the inflammatory and reparative responses following myocardial infarction and may function as danger signals." (PMID 24363498, 2013). "Tenascin-C (TN-C) is an extracellular matrix glycoprotein that is not expressed in normal adult hearts but is expressed in various myocardial diseases such as acute myocarditis, dilated cardiomyopathy, myocardial infarction, and myocardial hibernation." (PMID 24106506, 2013). "We show that our rationally customized TnC can improve function and performance in a common heart pathology–myocardial infarction (MI)." (PMID 26908229, 2016). "In mice, levels of fibronectin and of the ECM protein tenascin C, another MMP7 substrate, increase in response to myocardial infarction, but counterintuitively, this effect is less pronounced in MMP7 knockout mice." (PMID 40059514, 2025). "Tenascin-C (TN-C) is a glycoprotein of the ECM expressed during embryogenesis, tumorigenesis, and vasculogenesis, as well as in diseases such as myocardial infarction, LVH, and myocarditis." (PMID 33670747, 2021). "Members of MPs show different patterns of spatial and temporal upregulation during cardiac remodeling, such as TSP-1 in myocardial infarction, ventricular hypertrophy, and cardiac dilation, TSP-4 in ventricular hypertrophy and myocardial injury, and Tenascin C in tissue injury and fibrosis." (PMID 33451076, 2021). "TNC also contributes to fibrosis, and aggravatesfibrotic remodeling in cardiac tissue after myocardial infarction.Fibronectin-TNC aggregates are normally not present in the basement membranes butupon formation cause basement membrane thickening of retinal vessels in diabeticretinopathy." (PMID 39076867, 2023). "The purpose of this study is to evaluate the importance of tenascin-C ( TNC), N-terminal pro brain natriuretic peptide (NT-proBNP) and C-reactive protein (CRP) on LV remodelling after myocardial infarction (MI)." (PMID 22383923, 2012).
prostate carcinoma (21 papers, 2015 to 2025). A carcinoma that arises from epithelial cells of the prostate gland. "High levels of tenascin-C expression in prostate cancer stroma were also significantly associated with lymph node metastasis and clinical stage." (PMID 35740556, 2022). "TNC is an extracellular matrix glycoprotein, crucial for prostate cancer progression, and associated with prostate cancer bone metastases." (PMID 35948987, 2022). "Next, we evaluated the TNC expression in a tissue microarray of 210 primary prostate tissues, part of the European Multicenter High Risk Prostate Cancer Clinical and Translational research group (EMPaCT)." (PMID 33334054, 2020). "Increased alterations of TNC from our meta-analysis, in the NEPC dataset indicates the association of TNC with disease aggressiveness in prostate cancer with poor phenotype." (PMID 31798767, 2019). "Other ECM proteins such as tenascin-C, expressed in the nervous system during bone development and essential for wound healing in adults has been proposed as key hallmark of reactive stroma response in prostate cancer, promoting metastasis to bone through integrin α9β1." (PMID 39048763, 2024). "In prostate cancer, the TNC expression level can function as a potential biomarker for CAFs and is strongly associated with a poor patient prognosis." (PMID 40046232, 2025). "In prostate cancer cells, TNC expression is significantly positively correlated with the expression levels of key glycolytic enzymes, such as glucose transporter 1 and hexokinase 2 (HK2)." (PMID 40046232, 2025). "In BPH and prostate cancer, myofibroblasts and vimetin+/αSMA+ CAFs have been shown to secrete TNC in response to TGFβ signaling, epithelial cell-derived-IL-8 and/or tensile strain within the ECM." (PMID 36671452, 2022). "The data presented here suggest that AR-V7 transcriptionally regulates TNC expression in prostate cancer cells and TNC reciprocally induces AR-V7 protein stability and nuclear localization." (PMID 35948987, 2022). "It has also been shown that the expression of the glycoprotein tenascin-C is increased in the stromal microenvironment in human prostate cancer." (PMID 35740556, 2022). "It would follow that activated Src functions to promote splicing and protein stability of AR-V7, and up-regulates TNC expression in disseminated prostate cancer cells within the bone microenvironment." (PMID 35948987, 2022). "Reciprocally, both activated Src and AR-V7 were observed to upregulate autocrine TNC gene expression in prostate cancer cells." (PMID 35948987, 2022). "The differential role of AR-FL and AR-V7 in gene regulation is known; however, it is not yet understood if either AR-FL or AR-V7 transcriptionally regulates TNC expression in prostate cancer." (PMID 35948987, 2022). "Gene expression analysis presented in this study indicate that these upstream regulators of Src, including TNC, are induced in prostate cancer cells interacting with preosteoblasts." (PMID 35948987, 2022). "In prostate cancer, it has been shown that RNAi of cav-1 in benign prostatic myofibroblasts promotes tenascin-C gene expression, supporting a role for reduced or absent stromal cav-1 in increased tenascin-C." (PMID 28187162, 2017). "Some studies reported that tenascin expression is increased in prostate cancer stroma and tenascin-C significantly increased in stroma around neoplastic glands." (PMID 26042506, 2015). "Moreover, in prostate cancer, CSCs secrete tenascin-C to hinder the activation and proliferation of CD8+ and CD4+ T cells through interaction with α5β1 integrin located on T cells." (PMID 39671359, 2024). "Overall, the increased synthesis of tenascin-C predicts a poor prognosis in prostate cancer." (PMID 35740556, 2022). "Furthermore, inhibition of Src kinase activity resulted in downregulation of both AR-V7 splicing and TNC expression in prostate cancer cells." (PMID 35948987, 2022).
prostate carcinoma (continued). "Analogously, we speculate that Gal-3 and Tenascin-C may directly interact, thus mediating important steps of the metastatic cascade in prostate cancer." (PMID 33013832, 2020). "Involvement of TNC in the oncogenic process of prostate cancer is evolving." (PMID 31798767, 2019). "Tenascin C stood out as one of the biomarkers in various cancers, but its genomic status was unknown in subtypes of prostate cancers." (PMID 31798767, 2019). "Additionally, a3b1 integrin is able to restrain prostate cancer metastasis by regulating YAP/TAZ activity, and interestingly, stromal reprogramming promoted by the tumor may enhance prostate cancer metastasis by producing tenascin C via inhibition of YAP/TAZ." (PMID 35954292, 2022). "Tenfibgen (TBG), the carboxy-terminal fibrinogen globe domain of tenascin C, has been shown to home to tumors and to deliver anti-CK2 targeted therapies preferentially to tumor cells in xenograft models of human prostate cancer avoiding normal cells." (PMID 39394061, 2024). "Tenascin-C (TNC), an ECM glycoprotein, is a critical component of the reactive stroma that is expressed during the earliest phase of prostate cancer development." (PMID 35948987, 2022). "TNC is also reported to be significantly expressed alongside FSP1, αSMA and vimentin, and positively correlates with poor survival in patients with prostate cancer." (PMID 36671452, 2022). "Tenascin-C (TN-C), an extracellular matrix (ECM) glycoprotein, is highly expressed in various cancer cells, including ovarian, breast, and prostate cancer." (PMID 33855017, 2021). "As ASPN expression was increased in cribriform prostate cancer, this collectively suggests that ASPN expression was induced in NT5E+ASPN− fibroblasts, TNC+ASPN− fibroblasts, and PDGFRβ+ASPN− fibroblasts in the cribriform tumor microenvironment." (PMID 33600062, 2021). "As predicted, the MREs bound to tenascin C. Another study determined that ICAM-1, an intercellular adhesion molecule, was the target of scFv MREs selected on androgen insensitive prostate cancer cells." (PMID 26436100, 2015). "The percentages of NT5E+, TNC+, and PDGFRβ+ cells did not significantly vary between stroma adjacent to benign prostate glands and prostate cancer." (PMID 33600062, 2021). "Notably, TNC expression that is normally absent in mature adult bone has been shown to be expressed during prostate cancer bone metastasis, possibly facilitating prostate cancer cell homing to the bone marrow niche." (PMID 36671452, 2022). "Tenascin C (TNC), an extra-cellular matrix (ECM) family gene, is expressed in several cancer tissues of breast, lung, colon, and gastrointestinal tract leading to proliferation, migration, invasion, angiogenesis and metastasis, but its role in tumorigenesis of prostate cancer is poorly understood." (PMID 31798767, 2019). "TNC+ cells trended from ASPN− in benign adjacent stroma to ASPN+ in stroma adjacent to Gleason grade 3 and Gleason grade 4 with noncribriform morphology prostate cancer." (PMID 33600062, 2021). "Our results did not rule out the possibility that prostate cancer subtypes with alteration in ERG and MYC may exist in NEPC, without an involvement of TNC through alternative pathways." (PMID 31798767, 2019).
myocarditis (15 papers, 2013 to 2025). Myocarditis is a condition that is characterized by inflammation of the heart muscle (myocardium). "TNC has potential as a diagnostic marker and target for the molecular imaging of inflammation based on its specific expression, which may facilitate the differentiation of myocarditis from DCM." (PMID 34072423, 2021). "During acute myocarditis, IL-1β elevates the expression of matricellular proteins tenascin C (TN-C) and osteopontin (OPN)." (PMID 37175422, 2023). "It has been shown that the level of tenascin C expression is correlated with histologically proven inflammatory activity, suggesting that tenascin C may be a useful marker for assessing disease activity in myocarditis." (PMID 37835816, 2023). "In patients with myocardial injuries such as ischemia, myocarditis, and advanced heart failure, tenascin-C (Tn-C), an ECM glycoprotein, was transiently expressed in myocardial tissue, in association with immediate tissue repair response and the final deposit of collagen in the damaged tissue." (PMID 31275453, 2019). "Hence, immunostaining of tenascin-C could provide supportive evidence for myocarditis." (PMID 36378654, 2022).